USP8 (ubiquitin specific peptidase 8)
Diseases named in the same sentence as USP8 in open-access papers (continued):
Sharing a sentence is not in itself a finding about the gene and the disease.
adenoma (16 papers, 2016 to 2025). A neoplasm arising from the epithelium. "USP8 variant occurred in 14.3% (2/14) of functioning CCAs, 31% (9/29) of functioning SG and 48.5% (32/66) of functioning DG adenomas with significant difference between CCAs and DG tumors (p = 0.0344)." (PMID 41047423, 2025). "Similar to the most previous studies, the USP-8 mutated patients were women, presented with micro-adenoma and experienced recurrence after initial remission." (PMID 38862897, 2024). "USP8-mutated FCA patients presented with a significantly larger size of adenoma in a retrospective study." (PMID 38862897, 2024). "The somatic mutations in the USP8 gene are shown to be associated with Cushing’s disease and are usually detected in 20–60% of adenomas." (PMID 39684405, 2024). "A Sanger sequencing study of adrenocorticotropic hormone (ACTH)-secreting adenomas similarly observed 17 types of USP8 variants in 67 of 108 (~62%) ACTH-secreting tumor cells." (PMID 36834633, 2023). "Activating somatic variants of the gene encoding USP8 were recently found in 25–40% of ACTH-secreting adenomas causing CD." (PMID 35563252, 2022). "SMO is deubiquitinated by USP8 and this modification alters its target region, possibly linking this mutation to the already described mechanisms of USP8-mutated adenomas." (PMID 35743266, 2022). "In 2015, two different research groups reported the presence of various mutations in exon 14 of the USP8 gene in the majority of the analyzed corticotrope adenomas." (PMID 35743266, 2022). "In fact, we and others observed different molecular signatures in adenomas carrying USP8 variants compared to USP8-wildtype adenomas, and this carried over into increased POMC synthesis and ACTH secretion and changes in intracellular signalling." (PMID 32183012, 2020). "USP8 sequencing was performed in 111 adenoma specimens and 29 proved carriers of somatic mutations; in detail, 25 adenomas out of 84 specimens tested in culture carried USP8 variants as did 5 out of 38 specimens used in microarray analysis." (PMID 32183012, 2020). "ACTH-secreting adenomas carrying the USP8 mutation were significantly smaller than genome-wild adenomas, which indicated greater secretion of ACTH." (PMID 33537004, 2020). "In fact, findings reported so far on USP8 variant adenomas were collected almost exclusively in female patients; only two specimens were obtained from male patients, the remainder (80 USP8 variant adenomas in the four series) in female patients." (PMID 32183012, 2020). "Our research team had revealed a high prevalence (~60%) of USP8 mutations in ACTH-secreting adenomas." (PMID 33537004, 2020). "The incidence of EGFR expression in USP8-mutated adenomas was 80% as compared with 50% in wild type USP8 expressing tumors." (PMID 31845722, 2019). "Here, we performed further exome sequencing and identified recurrently-mutated genes including BRAF and USP48 in USP8 wild-type corticotroph adenomas." (PMID 30093687, 2018). "To date, 22 different USP8 mutations have been identified in 129 ACTH-secreting adenomas from 271 patients across three studies, with confirmation of USP8 mutation prevalence in later studies." (PMID 28487882, 2017). "In a subset of these adenomas, however, we observed an increased nuclear expression of USP8, a phenotype characteristic for the USP8 mutated human tumours, that correlated with smaller tumour size but elevated ACTH production in those tumours." (PMID 28005997, 2016). "Fifty-one percent (18/35) of adenomas harbor USP8 mutations." (PMID 39684597, 2024). "However, USP8-mutated adenomas showed significantly higher SSRT5 expression compared to the wild-type ones." (PMID 38862897, 2024). "Moreover, higher expression of heat shock protein 90 (HSP90) and an increase in the phosphorylation of the transcription factor CREB was observed in mutated-USP8 adenomas." (PMID 38862897, 2024). "Overall, the reported prevalence of USP8 mutations is 23–62% of corticotrope adenomas." (PMID 35743266, 2022).
adenoma (continued). "In addition, an overall prevalence of USP8 mutations of 32% has been reported in corticotropin-secreting adenomas." (PMID 33574795, 2020). "Therefore, ACTH-secreting adenomas with a USP8 mutation displayed higher expression of the EGFR, and increased mRNA transcription of proopiomelanocortin (POMC), which is the precursor of ACTH." (PMID 33537004, 2020). "Accordingly, we analysed the presence of USP8 hot-spot mutations in canine ACTH-secreting adenomas to answer the question whether USP8 mutations may also play a role in the development of corticotroph adenomas in dogs." (PMID 28005997, 2016). "Furthermore, somatostatin receptor 5 (SSRT5) was more frequent in USP8-mutated adenomas." (PMID 38862897, 2024). "Moreover, USP8-mutated adenomas were more likely to express SSTR5." (PMID 38862897, 2024). "However, macro-adenoma was more frequently seen in USP8-mutated patients." (PMID 38862897, 2024). "Interestingly, USP8 mutations seem to be much less frequent in SCAs, supporting the hypothesis of profound differences with Cushing’s disease adenomas." (PMID 35743266, 2022). "The objective of this study is to assess the impact of mutations identified within and outside the 14-3-3 binding motif in the USP8 gene in adenomas from CD patients on USP8 protein conformation in the context of Cushing’s disease." (PMID 39684405, 2024). "USP8-mutated adenomas showed higher level of POMC, CDC25A, MAPK4 but lower level of CCND2, CDK6, CDKN1B than USP8-wild-type tumors." (PMID 38862897, 2024). "USP8-mutated corticotrope adenoma cells are more sensitive to corticotrope modulators, namely CRH and dexamethasone, in vitro, compared to USP8-wild-type (WT) ACTH-secreting adenomas, with higher levels of CRH and glucocorticoid (NR3C1) receptors." (PMID 35743266, 2022). "Presence of USP8 mutations was analysed by Sanger and PCR-cloning sequencing in 38 canine ACTH-secreting adenomas." (PMID 28005997, 2016). "Immunohistochemistry staining of USP8 revealed that USP8 was localised in both the cytoplasm and the nucleus of normal pituitary and adenoma tissues." (PMID 28005997, 2016). "There was no statistical difference between the score intensity in normal pituitary vs. adenoma tissue (mean cytoplasmic USP8 2.16±0.40 vs 1.69±0.73, p = 0.12, respectively, and mean nuclear USP8 2.00±0.00 vs 1.57±0.80, p = 0.16, respectively)." (PMID 28005997, 2016). "Analysis of EGFR and USP8 staining intensities and clinical-pathological data of the respective adenomas revealed several correlations." (PMID 28005997, 2016). "All USP8-mutant adenomas were SST5-positive, and 73% of them were double-positive (SST5+/SST2+)." (PMID 39684597, 2024). "To uncover the possible molecular mechanisms that might be responsible for the differences between the USP8-mutant and USP8-WT adenomas, we performed transcriptome analysis." (PMID 39684597, 2024). "A recent study analyzed the different expression of microRNAs via RNA sequencing and cDNA analysis in formalin-fixed tumor samples; the authors found 68 differentially expressed microRNAs between the USP8-mutated and WT ACTH-secreting adenomas, with 400 putative target genes for these miRNAs." (PMID 35743266, 2022). "The preliminary findings of these studies suggest that the prominent epigenetic differences between USP8-mutated and WT corticotrope adenomas are not caused by the alteration of miRNAs expression." (PMID 35743266, 2022). "With the recognition of the importance of USP8 mutations, another two mutated genes in the mitogen-activated protein kinase (MAPK) pathway, USP48 and BRAF, have also been detected in corticotropin-secreting adenomas." (PMID 33574795, 2020). "Studies have revealed the mechanism of USP8-related secretion in ACTH-secreting adenomas." (PMID 33537004, 2020).
adenoma (continued). "Sanger sequencing of the DNA obtained from the first cohort of 18 canine ACTH-secreting adenomas revealed no mutation in the 14-3-3 binding site of the USP8 gene." (PMID 28005997, 2016). "USP8 in both normal pituitary and adenoma was expressed both in the cytoplasm and the nuclei." (PMID 28005997, 2016). "However, it remains unclear whether USP8 mutations and EGFR overexpression are associated with more aggressive adenomas." (PMID 34867776, 2021). "None of the analysed canine ACTH-secreting adenomas presented mutations in the USP8 gene." (PMID 28005997, 2016). "All mutant adenomas were SST5+, and most of them (8/11) were double-positive (SST2+/SST5+); only four out of the ten USP8-WT adenomas were SST5+, and two out of the ten were SST2+/SST5+." (PMID 39684597, 2024). "Out of the six SST5-negative USP8-WT adenomas, five were double-negative (SST2−/SST5−) and one was SST2+/SST5−." (PMID 39684597, 2024). "Analysis of transcriptome was performed for nine USP8-mutant and six USP8-WT adenomas and revealed the that the bidirectional dysregulation of Wnt signaling, including both the agonist RSPO2 and antagonist SFRP1, in the USP8-mutant corticotropinomas was downregulated." (PMID 39684597, 2024). "A total of 50% of USP8-WT adenomas were double-negative (SST5−/SST2−), and 40% of them were SST5-positive." (PMID 39684597, 2024). "Furthermore, the role of USP8 and EGFR protein expression was assessed by immunohistochemistry in a subset of 25 adenomas." (PMID 28005997, 2016). "However, while the USP8 staining was comparable in all normal pituitary samples, its expression profile (both cytoplasmic and nuclear) was highly variable in the ACTH-secreting adenomas compared to the normal gland." (PMID 28005997, 2016). "Finally, USP8 has been shown to increase Sonic Hedgehog (SHH) signaling by promoting SMO activity, even if the possible implications of this alteration have not been studied in USP8-mutated corticotrope adenoma cells to date." (PMID 35743266, 2022).
breast carcinoma (16 papers, 2019 to 2026). "USP8 reportedly deubiquitinates and stabilizes several substrate proteins such as HER2 and ERα, indicating that USP8 is crucial in the development and progression of breast cancer and the underlying mechanisms remain unclear." (PMID 40258843, 2025). "USP8 activation deubiquitinates YAP at K48-linked ubiquitination, leading to enhanced Hippo signaling and accelerated breast cancer progression." (PMID 41565619, 2026). "CCK8 and EdU incorporation experiments revealed that the depletion of USP8 suppresses breast cancer cell proliferation, which can be partially counteracted by YAP overexpression." (PMID 41565619, 2026). "In the meanwhile, studies from the same group have also shown that TGF-β, which promoted the exhaustion of CD8 + T cells in breast cancer, was regulated by ubiquitin-specific protease 8 (USP8)." (PMID 38884843, 2024). "Ubiquitin-specific protease 8 (USP8), also referred to as UBPY, is a deubiquitinating enzyme implicated in tumorigenesis of multiple cancer types, including breast cancer and glioma." (PMID 36816802, 2023). "Previous studies have shown that the USP8 inhibitor DUBs-IN-2 effectively inhibited the growth of breast cancer cells." (PMID 36816802, 2023). "USP8 promotes the progression of breast cancer via deubiquitinating and stabilizing Connexin-43 (Cx43) and Notch1 intracellular domain (NICD)." (PMID 35361778, 2022). "To validate the correlation between USP8 and TAK1 expression level in breast cancer cells, we analyzed protein and mRNA levels of USP8 and TAK1 in five breast cancer cells." (PMID 35361778, 2022). "Cell-based ubiquitination experiments showed that USP8 was able to remove ubiquitin modifications from TAK1 protein in breast cancer cells." (PMID 35361778, 2022). "Through our present results, we cautiously add that, in addition to Cx43 and NICD, TAK1 is another target of USP8 for its regulation on breast cancer progression." (PMID 35361778, 2022). "Taken together, these data demonstrate that USP8 positively regulates metastasis of breast cancer cells, providing a potential therapeutic target for breast cancer." (PMID 35361778, 2022). "Taken together, our study reveals Usp8 is a novel regulator of the JNK pathway, provides human USP8 as a promising drug target for JNK-related breast cancer treatment." (PMID 35361778, 2022). "In contrast, USP8 was downregulated in breast cancer and patients in USP8 high-expression group were correlated with better clinical characteristics." (PMID 34081623, 2021). "Indeed, when we knocked out the expression of USP8 (USP8-KO) in human breast cancer SUM159 cells, the transient expression of EGFP-2xFYVE confirmed that USP8 depletion caused EE enlargement." (PMID 39576689, 2024). "USP8 has also been proposed as a prognostic factor for breast cancer." (PMID 36816802, 2023). "Finally, we uncovered that human USP8 positively regulates breast cancer cell migration through stabilizing TAK1." (PMID 35361778, 2022). "Results revealed that USP8 positively correlated with TAK1 in different breast cancer cells." (PMID 35361778, 2022). "Finally, we demonstrated that knockdown of USP8 in human breast cancer cells suppressed cell migration and downregulated the JNK pathway activity." (PMID 35361778, 2022). "The inhibition of ubiquitin-specific protease 8 (USP8), a novel deubiquitylase of the Notch1 intracellular domain, downregulated the Notch signal pathway, resulting in the retardation of cell growth and colony forming ability of breast cancer cell lines." (PMID 36553667, 2022). "In view of Twist’s essential role in cell migration and breast cancer progression, future studies will be needed to delineate whether USP8 regulates cancer cell migration and cancer progression through Twist stabilization." (PMID 30918246, 2019). "Furthermore, endogenous USP8 was capable of pulling down endogenous TAK1 in breast cancer cells." (PMID 35361778, 2022).
breast carcinoma (continued). "Finally, we show that knockdown of USP8 in human breast cancer cells suppresses cell migration." (PMID 35361778, 2022). "In breast cancer, the type II TGF-β receptor TβRII is directly deubiquitinated and stabilized by USP8, which increases the expression of TβRII in the plasma membrane as well as tumor-derived extracellular vesicles (TEVs)." (PMID 37311739, 2023). "Moreover, MALAT1 inhibits ubiquitin-proteasomal degradation of the N-HER2 by affecting the binding of deubiquitinase USP8 and N-HER2, thereby promoting N-HER2 accumulation and trastuzumab resistance in HER2-positive breast cancer." (PMID 40258843, 2025). "In addition, several studies showed that NICD protein stability is also regulated by deubiquitinating enzymes such as USP7 and USP8 in T-ALL and breast cancer." (PMID 38043798, 2024). "Although our results clearly have demonstrated that USP8 suppresses migration of breast cancer cells, we do not examine whether USP8 regulates tumorigenesis in mouse model." (PMID 35361778, 2022).
pancreatic cancer (14 papers, 2023 to 2025). "The expression of USP8 was notably linked to the TNM stage in various pancreatic cancer patient cohorts." (PMID 38638430, 2024). "Targeting USP8 was found to sensitize pancreatic tumors to PD-L1-targeted immunotherapy, representing a potential therapeutic strategy for pancreatic cancer treatment." (PMID 40087690, 2025). "Recent studies have demonstrated that USP8‐mediated deubiquitylation of TβRII promotes tumor progression and immune suppression, thereby fostering a tumor‐permissive microenvironment in pancreatic cancer." (PMID 40952239, 2025). "For example, the study by Yang et al19 demonstrates that inhibition of USP8 expression effectively suppresses the growth of pancreatic tumors and that mice with knockdown of USP8 have a longer survival period." (PMID 40260316, 2025). "Collectively, targeting USP8 sensitizes tumors to PD-L1-targeted immunotherapy, offering a novel therapeutic strategy for pancreatic cancer patients." (PMID 41301681, 2025). "In solid tumors, including gastric, hepatocellular, cholangiocarcinoma, and pancreatic cancer, elevated USP8 expression suppresses anti-tumor immunity and drives tumor proliferation, invasion, and resistance to targeted therapies." (PMID 41301681, 2025). "For instance, the upregulation of USP8 in pancreatic cancer has been observed to deubiquitinate PD-L1, which can reduce PD-L1 levels by targeting USP8." (PMID 40990019, 2025). "Compared with normal tissues, pancreatic cancer tissues exhibit significantly elevated USP8 expression, and across multiple patient cohorts, USP8 levels positively correlate with tumor-node-metastasis (TNM) staging." (PMID 41301681, 2025). "The increased abundance of PD-L1 in PCa cells has also considered as one of the major causes of immune evasion of PCa, and it has been reported that PD-L1 is an downstream deubiquitinating substrate of USP8 in pancreatic cancer and non-small cell lung cancer." (PMID 40410130, 2025). "Combined treatment with a USP8 inhibitor and anti-PD-L1 therapy markedly inhibits pancreatic tumor growth, mediated through activation of cytotoxic T cells and the PD-L1/CD8+ T-cell axis." (PMID 41301681, 2025). "A USP8 inhibitor and anti-PD-L1 together significantly halted pancreatic tumor growth through the activation of cytotoxic T-cells." (PMID 38638430, 2024). "In pancreatic cancer, USP8 inhibits the ubiquitination-regulated proteasome degradation pathway by positively interacting with PD-L1 and upregulating its expression." (PMID 38654302, 2024). "In pancreatic cancer, USP8 levels were significantly higher in tumor tissues compared to normal tissues." (PMID 38638430, 2024). "Through the activation of cytotoxic T-cells, combining with a USP8 inhibitor and anti-PD-L1 therapy especiallly reduced the proliferation of pancreatic tumors and increased the antitumor immunogenicity." (PMID 37658402, 2023). "On one hand, pancreatic cancer tissues presented obviously higher USP8 levels and USP8 promoted the deubiquitination of PD-L1 protein." (PMID 37658402, 2023). "Therefore, USP8, as a deubiquitinating enzyme, represents a potential therapeutic target for pancreatic cancer." (PMID 40258841, 2025). "The increased abundance of PD-L1 could weaken the immune response of immune system, and PD-L1 has been reported as a downstream deubiquitinating substrate of USP8 in pancreatic cancer and non-small cell lung cancer." (PMID 40410130, 2025). "Similarly, a study on a USP8 inhibitor demonstrated its effectiveness in suppressing pancreatic tumor growth by activating killer T cells, especially when combined with anti-PD-L1 therapy." (PMID 38654302, 2024). "In pancreatic cancer, the deubiquitinase USP8 inhibits the degradation of PD-L1." (PMID 39223632, 2024). "Additionally, USP8 positively influenced PD-L1 expression by blocking its degradation in pancreatic cancer." (PMID 38638430, 2024).